CD4 (CD4 molecule)
Diseases named in the same sentence as CD4 in open-access papers (continued):
Sharing a sentence is not in itself a finding about the gene and the disease.
infection (continued). "When an infection occurs in vivo, the immune system, including CD4+ T cells, neutrophils, NK cells, and macrophages, work together to coordinate an antifungal response." (PMID 36444627, 2022). "They assumed logistic growth for healthy CD4+ T cells and a saturated incidence rate for V-T-C infection in the form ψ1HnPan+Hn, where n≥1 and a>0." (PMID 36016341, 2022). "CD101+ CD4 T cells are severely depleted during acute SIV infection (14 days post-infection), with a mean 2.6-fold reduction in the frequency of blood memory CD4 T cells expressing CD101." (PMID 35867722, 2022). "TNF receptor-associated factor 3 (TRAF3) was shown to be recruited in the TCR/CD28 signalling complex in murine CD4+ T cells and critical for T cell-mediated immunity to infection." (PMID 35142878, 2022). "IL-8 expression was also significantly higher in active MABS infection compared to control cohorts for CD4+ T cells (p=0.004) and CD8+ T cells (p=0.05), indicating a strong association with MABS species infection." (PMID 36439147, 2022). "When responding to an infection, CD4 T cells are critically important for providing help to CD8 T cells and B cells as well as mediating cytotoxic activity directly." (PMID 36119079, 2022). "The median number of unique SARS-CoV-2 CD4+ T cell clonotypes increased from 21 (range: 4–62) after natural infection to 38 (range: 12–75) after vaccination." (PMID 35533495, 2022). "Upon pathogen infection, the functional specialization of CD4+ T cells is determined according to the antigen signals and microenvironmental cues." (PMID 36282845, 2022). "Our results establish this study as a pivotal element in the understanding of impaired CD4 T-cell immune response upon infection." (PMID 35392090, 2022). "Numbers of iNKT cell subsets remained stable during infection except for a significant expansion of GATA3-Tbet-/+ CD4+ cells at day 14 pi and day 5 pri." (PMID 36159876, 2022). "During ADA treatment, she contracted HIV from sexual exposure and showed elevated HIV-RNA replication and decline in CD4+ lymphocyte counts during the early stages of infection." (PMID 35990692, 2022). "These mice are able to efficiently control infection whereas BALB/c mice develop a type 2 helper (Th2) CD4+ T cell response and fail to recover." (PMID 36034693, 2022). "During infection of primary CD4+ T cells or SupT1 T cells with HIV-1 BRU, replication efficiency of the virus carrying IN S57A mutant was seriously decreased due to decreased integration, while reverse transcription and virion production were not affected." (PMID 36293197, 2022). "This indicated that there was enhanced CD4+ T cell priming at week 2 post infection in Mtb-HT1 infection as the appearance of CD4+CD69+ T cells is the first evidence of CD4+ T cell priming in the lymph nodes during Mtb infection." (PMID 35173157, 2022). "Through experimental-mathematical investigations, we have previously shown that cell-to-cell infection is predominant in the human CD4+ T-cell culture system and this mode of infection increases viral fitness by 3.9-fold." (PMID 35468127, 2022). "At the site of infection, an increase in the frequency of CD4+IFN-γ+ T cells was consistently observed in the ears of Mrp8;Metfl/fl compared to control mice, although it was not statistically significant in all experiments." (PMID 35041723, 2022). "Although the inefficient infection in CD4+ TRM cells can be blocked during the HIV replication cycle, the indirect cell-to-cell transmission gives way to HIV-1 latency." (PMID 35664434, 2022). "Results showed a more severe and prolonged acute phase of infection in mice with DM with altered recruitment of lung CD4+ T cells and altered secretion of cytokines particularly increased IL17." (PMID 35888567, 2022). "The reservoir of latent HIV can be established in the early stage of infection and is mainly composed of CD4+T cells with resting memory." (PMID 35967854, 2022).
infection (continued). "The CD4+ arm of the immune system plays an orchestrating role, rather than effector or killer role, therefore they cannot directly prevent infections." (PMID 36045689, 2022). "We recently investigated the impact of Eomes expression by CD4 T cells responding to IAV because the infection drives effector responses marked by cytokine production and cytotoxic activity that have been shown to be impacted by Eomes in other models." (PMID 36358898, 2022). "Following influenza virus infection, CD4 CTL development at the site of infection required expression of the transcriptional repressor Blimp-1 in addition to upregulation of T-bet." (PMID 35903098, 2022). "We described that HIV-1 Envs of VNPs, Progressors and RPs patients are equally functional for CD4-mediated pore fusion formation, viral transmission, virus entry and infection, and for productive signaling as well." (PMID 36140273, 2022). "CD4+ proliferative responses remained largely cross-reactive to Omicron spike, with only 12% (4/33) of individuals with prior infection and/or vaccination and/or booster showing a >50% (0.3log10) reduction." (PMID 35202566, 2022). "Based on logistic regression, we found that higher pre-existing influenza virus-specific CD4 and CD8 T cell responses were associated with lower infection odds for corresponding subtypes." (PMID 35858844, 2022). "The liver empties most of the intestine blood and is the leading site of CD4+T lymphocytes reduction and increase in the virus in the initial stage of infection." (PMID 35956604, 2022). "Infection of the mice with wild-type HTLV-1/2 viruses resulted in preferential T-cell transformation (CD4+:HTLV-1 and CD8+:HTLV-2)." (PMID 35062342, 2022). "Accordingly, infection with human immunodeficiency virus type 1 (HIV-1) determines the establishment of the viral DNA reservoir of long-lived CD4+ cells." (PMID 35558085, 2022). "Consistent with productive infection, we also observed downregulation of CD4 expression on target cells that was most pronounced in the resting memory T cell population." (PMID 35417711, 2022). "As already observed in the context of natural infection, also the frequencies of mRNA- or viral vector-induced CD4+ T cells specific for Alpha or Beta reference pools were significantly lower than those specific for the entire ancestral Spike protein." (PMID 35154116, 2022). "In contrast to the CD8+ T-cell response, the spike-specific CD4+ T-cell response showed a more limited repertoire of targeted epitopes after vaccination compared to infection (bottom)." (PMID 35484232, 2022). "Cellular infection is initiated when viral gp120 binds to CD4 and a coreceptor (CCR5 or CXCR4), leading to gp41-mediated membrane fusion." (PMID 35714165, 2022). "We demonstrate that vaccination and infection induce robust CD4+ and CD8+ T cell responses that largely cross-react with Omicron, consistent with recent work from our laboratory and others on limited T cell escape by Beta, Delta and other variants." (PMID 35102311, 2022). "Much of the evidence from clinical CE patients suggests that T-cell control of established infections (established phase) is dominated by CD4+ T cells." (PMID 36046744, 2022). "We first quantitated live bacteria in the mediastinal lymph node (MdLN) on day 14 post infection, corresponding to the onset of antigen-specific CD4 T cell priming." (PMID 35695454, 2022). "As expected, prior to and shortly after infection the homing of transferred virus specific OT-II CD4+ T cells into ICAM-1/2-/- MedLNs was markedly impaired." (PMID 36895258, 2022). "Overexpression of TIGIT by lentivector infection of human CD4+T cells, the cell proliferation, cytokines secretion (IL-12, IFN-γ, and TNF-α), and T-bet expression were significantly hindered whereas IL-10 production was enhanced." (PMID 35720417, 2022).
infection (continued). "While strong humoral responses are indicators of protection from infection and transmission, T cells mediate or “help” such antibody responses (CD4 T helper cells) as well as protect from severe disease by clearing all infected cells (CD8 cytotoxic T cells)." (PMID 35990661, 2022). "CXCL10 is a primary IFN-γ-inducible immunomodulatory cytokine with a role in homing activated Th1 CD4+ T cells to sites of infection or inflammation." (PMID 35743825, 2022). "Surprisingly, E. granulosus s.s. infection resulted in increased IL-10 expression in hepatic or splenic CD8+ T cells from CD4 knockout mice and decreased granzyme B or IFN-γ expression." (PMID 36046744, 2022). "To study that, we performed ex vivo infection experiments of primary CD4+ T cells and measured cell proliferation after IC engagement by flow cytometry." (PMID 35616530, 2022). "The IEC HIV trans‐infection capacity was assessed upon co‐culture with CD3/CD28‐activated CD4+ T‐cells." (PMID 35916394, 2022). "To verify the accuracy of data projection into our reference map, we analyzed an independent scRNA-seq dataset of LCMV-specific CD4+ T cells isolated at 7 and 30 days post-infection with LCMV Armstrong." (PMID 35829695, 2022). "Conversely, infection with Plasmodium results in increase in number and activation state of CD4 + T cells, creating an ideal environment for HIV replication, increasing viremia." (PMID 36504775, 2022). "A significantly higher rate of bacterial infection (39.8%) was observed in participants having CD4 count < 200 cells/μl as compared to the least infection in those with CD4 count > 500 cells/μl." (PMID 35672713, 2022). "The importance of Tregs in RSV disease has also been shown in murine models, where abrogating Tregs prior to infection led to greater disease severity, enhanced CD4/CD8 T cell responses, and lung eosinophilia compared to WT mice." (PMID 35406717, 2022). "Following the resolution of infection, a residual population of memory CD4+ T cells remains within the circulation or in tissues that persists long term and provides protection from reinfection." (PMID 35858332, 2022). "Both FACS and scRNA-seq studies revealed that infection-induced specific (mainly spike-specific) CD4+ T cell responses showed memory characteristics, including subsets with TH1, TH17 and TFH phenotypes." (PMID 36119105, 2022). "Several countries have used models based on CD4+ T cell values close to diagnosis to estimate the number of incident infections." (PMID 35544888, 2022). "Our data showed that either CD4+ or CD8+ memory T cells responses are significantly higher in the severe groups at 1-year after infection." (PMID 35240947, 2022). "In this study, we found that the infection rate of T.marneffei was 10% in HIV-1 infected patients with CD4+ Tcell counts less than 1500 cells/μl, 17% in those less than 200 cells/μl, and 22% in those less than 100 cells/μl." (PMID 35639503, 2022). "At 7 d.p.i., we observed comparable parasite numbers in the spleens of both infection routes, so we decided to assess splenic DC maturation as well as IFNγ production by CD4 and CD8 T cells via flow cytometry." (PMID 35898505, 2022). "Surprisingly, we uncovered elevated FcγRI on CD3+ T cells and its CD4+ T cell subsets following infection." (PMID 36677333, 2022). "We found that Tcf7, which encodes Tcf1 and is involved in early induction of Bcl6, was downregulated under HIVYu2b infection in all CD4+ T cell transitions toward the TfhD3 profile." (PMID 34984326, 2022). "At day 2 after infection, we cocultured the CD4+ T cells infected with HIV-WT or HIV-ΔNef with the expanded CD8+ T cells." (PMID 35133986, 2022). "The production of cytokines by CD4 T cells is one way by which information about the nature of an infection is conveyed to B cells, resulting, for example, in differential antibody isotype class‐switch recombination." (PMID 35801309, 2022).
infection (continued). "Recent studies have shown that SARS-CoV-2-specific CD4+ T cell responses are maintained up to 10–12 months following infection or even more, because we were able to identify virus-specific Th cells 15 months PSO in several individuals." (PMID 36146622, 2022). "Within the lung, the CD4 T cells are localized to both lung vasculature and tissue but are highly enriched in the lung tissue after infection." (PMID 35215193, 2022). "Models of vaccination and infection suggested the role of CD4+ T cells and their Th1 cytokine profile." (PMID 36177012, 2022). "As the bacteria were cleared from the FRT during the second and third week of infection, the number of these responding CD4 T cell declined." (PMID 35196366, 2022). "In mammals, upon encountering an intracellular pathogen infection, naïve CD4+ T cells preferentially differentiate into Th1 cells, which predominantly produce IFN-γ and lymphotoxin, leading to the eradication of intracellular pathogens." (PMID 36282845, 2022). "Treatment with amitriptyline (180 mg/l via drinking water for 14 days before infection and 10 days during infection) enhance frequencies of CD4+IL-17+ and CD4+IFN-γ+ T-cells cells through acid sphingomyelinase inhibition." (PMID 36189272, 2022). "We also found in the ankle joints of PD-1-/- mice, there was an increase in both CD4+ T cells at week eight post-infection and CD8+ T cells at weeks two and four post-infection." (PMID 36265003, 2022). "What’s more, for total CD4+ T cells, infection rate decreases somewhat after 16 h while it remains essentially unchanged in total CD8+ T cells." (PMID 35317717, 2022). "It afforded some protection against challenge infection with Mtb in mice and boosted BCG-induced immunity and protection in association with an enhancement of production of multifunctional CD4+ T cells." (PMID 36267175, 2022). "In the first days of infection, the VirB operon contributes to the Th1 polarisation of CD4+ T cells in B. abortus-infected mice." (PMID 35888979, 2022). "In our study, a pivotal role of CD4 CTL in protecting against transplacental infection was distinguished." (PMID 36798517, 2022). "At seven months post infection the frequencies of CD4+ Tem were higher than at baseline in all organs studied." (PMID 36275685, 2022). "For the same reason, the observed decrease in infection following treatment of the DC/CD4+ T-cell co-culture with TNTi is entirely related to the inability of DCs to reticulate." (PMID 35204813, 2022). "Once a DC has been infected or has processed HIV-1 antigens, such as macrophages, it is able to transmit the infection to CD4+ T cells through mechanisms such as the formation of virological synapses." (PMID 36146843, 2022). "In a series of five repeated experiments, peak CD4 T cell infection on day 7 averaged 26 ± 4% (mean ± SEM)." (PMID 35895672, 2022). "γδT cells can rapidly produce IL-17A in the early stage of Mycobacterium tuberculosis infection, and last for 4 weeks, while CD4+T cells only produce IL-17 within the first 2 weeks of infection." (PMID 35665407, 2022). "As expected, there was a marked increase in the frequency of IL-4-producing CD4+T cells in the blood (P<0.001), LN (P<0.01), and spleens (P<0.001) of WT rats following infection with S. japonicum." (PMID 35584107, 2022). "Contrary to the CD4+ TRM cells studied in mouse vagina which reduced the risk for HSV, this human tissue-resident subset supported the infection with HIV-1." (PMID 35488095, 2022). "It is the first compartment for CD4+ T cell depletion in new infections and is rich in virus-permissive immune cells, including dendritic cells, macrophages and activated CD4+ T cells." (PMID 36432041, 2022). "CD4 T cells play a critical role in immune protection by recruiting neutrophils, eosinophils, and basophils to the site of infection and responding to a full range of immune responses by producing cytokines and chemokines when the body was infected." (PMID 36016957, 2022).
infection (continued). "We found that at week 2 post infection, consistent with rapid priming in the lymph nodes, there was an increase in the total number of CD4+ T cells in the lungs of Mtb-HT1 infected mice compared to Mtb-LT1." (PMID 35173157, 2022). "In hepatic iNKT cells IL-13 production during infection was linked to GATA-3+T-bet+ CD4+ and CD4- subsets while IL-4 and IFN-γ was produced by GATA-3+T-bet+ as well as GATA-3-Tbet+/- cells." (PMID 36159876, 2022). "Therefore, the association between increased CD4+ T-cell responses in convalescent individuals and disease severity likely reflects more abundant and prolonged antigen stimulation and consequent expansion of the adaptive immune response during the acute phase of the infection." (PMID 36068292, 2022). "Together this points to the importance of stringent regulation of CD4+ T cells in defense against MT infection." (PMID 35359994, 2022). "In the mouse models infected with SARS-CoV-2, CD4+ T-cell responses showed a critical role in limiting infection." (PMID 35286241, 2022). "This is due to the fact that a low CD4 count makes it challenging for the body to combat additional infections, making even a straightforward infection like a cold significantly worse." (PMID 36319734, 2022). "APOBEC3G expression level in PBMCs has been reported to be correlated with VLs or CD4 T cell counts during primary infection." (PMID 36380676, 2022). "In CD4+ Jurkat T cell lines, intracellular viral RNA and antigens are detected following infection; however, the amount virus released slowly decays, and after several passes of supernatant fluids to new, uninfected cells, the infection is lost." (PMID 35707535, 2022). "HIF-1α was expressed in HIV-1 infected primary CD4+ T cells in higher levels than mock infected cells 48 hours post infection." (PMID 36467738, 2022). "In HIV infected hDRAGA mice, HIV RNA+ cell numbers were elevated in CD20hi areas; however, when CD4+ T cell density was considered, the tendency for preferential infection within CD20hi areas was reduced in spleen and ablated in mesenteric lymph nodes." (PMID 36505432, 2022). "MLN and lung cells of two individual Nippostrongylus brasiliensis (Nb)-infected IL-4eGFP reporter mice (4get B6) were sorted for IL-4eGFP+CD4+ cells 10 days post infection." (PMID 35950748, 2022). "Recently, it has been demonstrated that animals immunized with P. brasiliensis EVs presented higher levels of activated CD4+ T lymphocytes in the BAL after infection." (PMID 35719346, 2022). "Consistent with our previous observations of high Id3 expression by naive CD8+ T cells, prior to infection more than 95% of CD4+ T cells expressed Id3-GFP." (PMID 35858332, 2022). "This study also detected IFN-γ-producing CD4+ T cells in the rGP19-immunized mice and then were later infected with E. canis on day 14 of the post-infection period using flow cytometry." (PMID 36006302, 2022). "At 14 days following cell infection and stimulation, CD4 T cell subpopulations that had undergone varying degrees of proliferation, were isolated by flow cytometric cell sorting, based on their CFSE staining profiles." (PMID 35895672, 2022). "We found the majority (64.7%) of HIV Ab/Ag positive patients requiring LTC were diagnosed with very late stage infection (CD4 < 200) and heterosexual (58.8%)." (PMID 36357472, 2022). "Previous studies of the leishmanization model have shown that resolution of acute infection with LmWT parasites (12–20 weeks post-infection) is accompanied by the formation of CD4+ TRM cells that contribute to protective immunity against virulent challenge." (PMID 35419001, 2022). "HuDRAG-A2 and huNRG mice infected with HIV also showed significant depletion in human CD4+ T cells in the blood at 8 weeks post-infection." (PMID 36146734, 2022). "Another Candida-specific subset of CD4+ T cells expressing IL-22 (Th22) is found in humans as memory cells and is increased following infection." (PMID 36177012, 2022).